HIF1A (hypoxia inducible factor 1 subunit alpha)
Diseases named in the same sentence as HIF1A in open-access papers (continued):
Sharing a sentence is not in itself a finding about the gene and the disease.
breast cancer (continued). "Similarly, BCRT1 is an M2 polarizing lncRNA that is upregulated in response to tumor hypoxia and leads to breast cancer progression via novel HIF-1α/lncRNA BCRT1/miR-1303/PTBP3 pathway." (PMID 33763348, 2021). ", Arctigenin (from Arctium lappa L.), and cyperenoic acid (from Croton crassifolius Geiseler) can inhibit the tube formation of HUVECs in vitro and exhibit antiangiogenesis of breast cancer in vivo by inhibiting the expression of angiogenic growth factors and HIF-1α/VEGF signal pathway." (PMID 35145409, 2021). "Additionally, a microRNA, miR-18a has been implicated in diabetes- breast cancer crosstalk and it reportedly target HIF1-α, and YC-1 is a specific HIF1-α signaling inhibitor by blocking HIF1-α synthesis." (PMID 34225729, 2021). "Many researchers have demonstrated that high HIF-1α expression is found in most human tumours, such as breast carcinoma, hepatocellular cancer, cervical cancer and colorectal tumours, and HIF-1α may also be a prognostic marker in patients with oral cancer." (PMID 34256803, 2021). "As the function of MB in carcinoma cells seems to be different from those in muscle cells and because of rising evidence of a functional correlation between MB and transcription factor HIF-1α, we verified the cellular localization of MB in breast carcinoma cells." (PMID 34671319, 2021). "Our results may bring insights to the HIF‐1α/STAT3 interaction in breast cancers and suggest sanguinarine as a promising candidate for HIF‐α/STAT3 inhibition." (PMID 32065498, 2020). "We found that HIF‐1α levels were significantly lower in alpinetin treatment cells, which are a central regulator of a global metabolic transcription programme and participate in the development of breast cancer." (PMID 32562470, 2020). "Other studies have shown that HIF-1α is a driver of drug resistance in breast cancer." (PMID 33266219, 2020). "Our findings regarding phagocytosis are divergent from previously reported work on breast cancer but are in line with other results showing that macrophagic HIF1α enhances phagocytosis, suggesting that this might be a feature dependent on the cancer type." (PMID 32231135, 2020). "Combined, these factors suggest that breast cancer brain metastases face both more profound and more widespread hypoxia versus primary tumors, potentially contributing to their increased dependence on HIF1A signaling for proliferation." (PMID 33298946, 2020). "Next, MCF-7 cells and T47D cells were employed to further elucidate whether HIF-1α participated in the process of LNT-mediated breast cancer suppression." (PMID 33245358, 2020). "That increased hypoxic and HIF1A signaling in CTCs predicts poor clinical outcome in breast cancer patients with brain metastases further highlights the importance of these pathways in brain metastasis progression and confirms the clinical relevance of our findings." (PMID 33298946, 2020). "Furthermore, overexpression of FBP1 can suppress the expression of HIF-1α in MDA-MB-468 breast cancer cells exposed to hypoxic conditions." (PMID 32408596, 2020). "Taken together, these results suggest that HIF1A signaling may play an important role in the proliferation of breast cancer cells in the brain." (PMID 33298946, 2020). "Indeed, HIF1α overexpression stimulates bone metastases of breast cancer cells, whereas knockdown of HIF1α showed a decrease of metastatic growth." (PMID 32092997, 2020). "Moreover, there is an interesting phenomenon in which increasing the release of exosomes containing miR-210 by breast cancer cells promotes their invasion and assists in their survival, which is hypoxically mediated by the HIF-1α oxygen-sensing system." (PMID 32014012, 2020). "Altogether, these results suggested that the increased expression of GRK2 noted in the breast cancer cell lines and in patients, would also contribute to tumor progression by fostering the cellular mechanisms that induce and stabilize the HIF-1α protein in normoxia." (PMID 32413989, 2020).
breast cancer (continued). "HIF‐1α is upregulated in multiple human cancers, such as ovarian, prostate, and breast cancers." (PMID 32436609, 2020). "HIF-1α reduces the sensitivity of breast cancer cells to tamoxifen." (PMID 33362547, 2020). "NRF2 silencing in breast cancer reduced HIF-1α accumulation and metabolic rewiring." (PMID 33266219, 2020). "Our results may bring insights to the HIF‐1α/STAT3 interaction in breast cancers and suggest sanguinarine may potentially be recognized as HIF‐1α/STAT3 targeted compound for disturbing the growth of human breast cancers." (PMID 32065498, 2020). "HIF-1α was found to regulate TGF-β-SMAD3 pathway in breast cancer patients." (PMID 32322559, 2020). "For example, it has been demonstrated that the expression level of HIF-1α in breast cancer and other tumor tissues is significantly higher than that in adjacent tissues, and its increase is positively correlated with the incidence of breast cancer metastasis and mortality." (PMID 33344235, 2020). "HIF‐1α is the master transcriptional regulator mediating the adaptive responses to intra‐tumoral hypoxia to drive cancer progression, particularly in breast cancer, which the efficiency of cellular oxygen utilization is lower than normal cells in its microenvironment." (PMID 32562470, 2020). "Thus, we propose that CLDN6 plays an anti-metastatic role in breast cancer by antagonizing the SENP1/HIF-1α signalling pathway." (PMID 32093760, 2020). "To further validate the relationship between miR526b, miR655, and HIF-1α expression, we tested our hypothesis on human breast cancer tissues." (PMID 32707933, 2020). "Leptin stimulation facilitates VEGF expression in breast cancer cells via HIF-1α and NF-κB." (PMID 33123472, 2020). "Western blotting showed that HIF‐1α and Kindlin‐2 were both upregulated in breast cancer." (PMID 32436609, 2020). "Furthermore, tumor-associated macrophages (TAMs) enhance the aerobic glycolysis and apoptotic resistance of breast cancer cells via the extracellular vesicle (EV) transmission of a myeloid-specific lncRNA, HIF-1α-stabilizing long noncoding RNA (HISLA)." (PMID 32754302, 2020). "Given that LNT-mediated HIF-1α inhibition depended on Nur77, it may be inferred that the anti-tumor effect of LNT on breast cancer is through regulating immune response via the Nur77/HIF-1α axis." (PMID 33245358, 2020). "HIF-1α activity has been linked to the upregulation of fatty acid binding protein 7 (FABP7), which is involved in fatty acid uptake, binds to unsaturated fatty acids, and contributes to breast cancer tumorigenesis." (PMID 33266219, 2020). "LNT was reported to inhibit the proliferation of breast cancer cells, but whether HIF-1α was involved in this process remained unknown." (PMID 33245358, 2020). "Although CXCL12, CCL2, VEGF, MMP2, LOX, and CXCR4 were highly associated with HIF-1α expression, their prognostic significance in breast cancer is less so they were not chosen for further immunohistochemistry analyses." (PMID 33003428, 2020). "In addition, hypoxia-inducible factor 1-α (HIF1-α) in breast cancer negatively regulates PCK2 at the transcriptional level causing breast cancer tumor-repopulating cells (TRCs) to grow in anoxic environments." (PMID 33142842, 2020). "Since previous results had already indicated that HSF4 can modulate the expression of HIF-1α in MCF-7 breast cancer cells, it is possible that, similarly to HSF2, the function of HSF4 is hijacked in HCC in order to enhance HIF-1α expression, thereby allowing cancer progression." (PMID 32408596, 2020). "We found that CLDN6 was transcriptionally upregulated by HIF-1α in three breast cancer cell lines." (PMID 32093760, 2020). "HIf1α is a common factor in the development of different tumors and breast cancers." (PMID 32373503, 2020). "Furthermore, elevated HIF-1α level is a predictive marker of early relapse and metastasis, and correlated with bad clinical outcome in human breast cancer." (PMID 33489906, 2020).
breast cancer (continued). "Interestingly, leptin is also involved in the regulation of VEGF in breast cancer cells via hypoxia-inducible factor 1α (HIF-1α) and NF-κB signaling promoting cancer progression." (PMID 32092997, 2020). "The aim of the present study was to investigate whether LNT administration suppresses the growth and metastasis of breast cancer by inhibiting HIF-1α, and whether this effect is Nur77-dependent." (PMID 33245358, 2020). "A possible explanation for this observation may lie in the ‘reverse Warburg effect’ model and the role of HIF-1α activation in breast cancer cells proposed by Lisanti and colleagues." (PMID 33148314, 2020). "Studies on Notch-mediated hypoxia-induced EMT mainly concentrated on breast cancer cells, which showed Notch worked closely with HIF-1α in hypoxia-induced EMT and the inhibition of Notch could effectively block EMT induction." (PMID 32322559, 2020). "However, little is known about the expression status of HIF‐1α in breast cancer and the relationship between HIF‐1α, Kindlin‐2, and breast cancer stiffness." (PMID 32436609, 2020). "Recently, a study showed parkin expression is inversely correlated with HIF-1α expression in breast cancer, and parkin could interact with HIF-1α and promote HIF-1α degradation through ubiquitination." (PMID 32328124, 2020). "Importantly, our results in the second model of advanced breast cancer disseminating to the lungs, suggest selective upregulation of HIF‐1α by MTD chemotherapies, similarly to colonic metastases to the liver." (PMID 32686360, 2020). "HIF-1α activates the expression of VEGF in breast cancer and in NSCLC." (PMID 31952335, 2020). "HIF1A is associated with macrophage function, whereby its overexpression induces macrophage M1 polarization, and it also plays a role in centrosome aberrations and tumour progression in TNP breast cancer." (PMID 32370743, 2020). "However, the inhibited metastasis was rescued by restoring HIF-1α in the CLDN6-overexpressing breast cancer cell lines." (PMID 32093760, 2020). "We further verified the effects of hypoxia enhancing miRNA-induced oxidative stress, cell migration, induction of EMT, expression of hypoxia-linked genes such as VHL, HIF-1α, and NFκB1, and expression of inflammation-associated genes such as VEGFA, COX-2, and EP4 in breast cancer cell lines." (PMID 32707933, 2020). "Because K391 and K477 SUMO sites are required for SENP1-regulated HIF-1α deSUMOylation, we wondered whether mutations in the SUMO site in HIF-1α would prevent the effect of CLDN6 overexpression in breast cancer cells." (PMID 32093760, 2020). "It was reported that SOCS6 could decrease the protein levels of p-STAT3 and HIF-1α in breast cancer and hepatocellular cancer." (PMID 32519748, 2020). "In hypoxic breast cancer cells, oxidative stress-induced overexpression of miR-181c blocked HIF-1α accumulation and diminished hypoxia-inducible levels of glycolysis enzymes, including glycolysis-associated glucose transporter-1 (GLUT1), hexokinase 2 (HK2), PDK1, and lactate dehydrogenase A (LDHA)." (PMID 35006436, 2020). "By binding miRNA let-7 higher expression of H19 in hypoxia promotes the release of HIF-1α in hypoxic breast cancer stem cells eventually resulting in elevated expression of pyruvate dehydrogenase kinase 1 (PDK1) and consequently enhanced glycolysis and stemness." (PMID 32640630, 2020). "In human breast cancers, a SIRT3 deficiency can stabilize HIF-1α." (PMID 33117804, 2020). "Interestingly, crosstalk from TAMs to breast cancer cells by exosomes regulates HIF‐1α‐mediated aerobic glycolysis metabolism and contributes to tumor progression in breast cancer." (PMID 32521117, 2020). "Additionally, growth factor signalling via the HER3 ligand neuregulin-1β has been shown to drive HIF-1α levels in normoxia through increases in protein translation and stability in breast cancer cell lines." (PMID 30670058, 2019). "HIF-1α upregulates CD47 expression in breast cancer to enables evasion of macrophages." (PMID 31394796, 2019).
breast cancer (continued). "Furthermore, HIF-1α-induced transcriptional reprogramming in breast cancer cell triggers pluripotency markers, which contribute to tumour expansion in vivo." (PMID 31052256, 2019). "Furthermore, a breast cancer study links hyaluronan over-expression to increased HIF-1α production through upregulated glycolytic flux." (PMID 31272438, 2019). "In addition to tumor hypoxia, downregulation of antioxidant systems in breast cancer cells further potentiates ROS production through the loss of SIRT-3 function induced by the accumulation of mROS and the stabilization of HIF-1α." (PMID 30754624, 2019). "Notably, the introduction of a miR-181c inhibitor in NRF2-silenced breast cancer cells restored HIF-1α accumulation and HK2 elevation following hypoxic incubation." (PMID 31078780, 2019). "Future studies will need to determine the exact mechanism of hypoxic glycogen accumulation based on glycogen synthase and glycogen phosphorylase regulation and the possible relation to HIF1α stabilization under hypoxia in breast cancer, in a context dependent manner." (PMID 31536495, 2019). "The altered gravity-based transcriptome changes could be confirmed by measurements of HIF-1α protein expression levels in the breast cancer cell line MDA-MB-468 performed in an independent hardware on the First Swiss Parabolic Flight." (PMID 30669540, 2019). "Our study is the first to reveal that SOX2 and NEDD9 may function as novel upstream regulators of Rac1/HIF-1α in hypoxic breast cancer cells." (PMID 31462898, 2019). "Finding out whether the effect of HIF-1α on tamoxifen-sensitivity and breast cancer survival is depending on down-stream EGFR-signaling is key in this respect." (PMID 31821370, 2019). "It has also been shown that B7-H3 could regulate aerobic glycolysis via HIF-1α in breast cancer cells." (PMID 30952834, 2019). "These two pathways may act in cooperation to promote breast cancer progression, as assessed by clinical studies showing that HIF-1α and hypoxia gene signature were correlated with poorer survival in response to hormone therapy." (PMID 31052524, 2019). "Taken together, these results suggest that DNMT3a may be the primary protein responsible for methylation of CpG and non-CpGs sites in the HIF-1α gene promoter around TSS and, thus, suppresses HIF-1α expression in luminal breast cancer." (PMID 30940798, 2019). "Recently, it was showed that MSC-derived exosomes with miR-100 cargo could modulate mTOR/HIF-1α signaling axis in recipient breast cancer cells, resulting in a decrease in VEGF expression." (PMID 30925935, 2019). "Moreover, Liang H. and colleagues investigated miR-153 mechanism of action in breast cancer; showing that this miRNA acts as a tumor suppressor by targeting HIF-1α." (PMID 31627322, 2019). "There was a greater difference in disease progression and breast cancer survival when the HIF Pathway score was used than when HIF-1α protein was considered, supporting the use of the pathway score as a robust marker of HIF-1 transcriptional activity and, potentially, patient prognosis." (PMID 30943919, 2019). "Although a recent study showed that knockdown of HIF-1α decreased hypoxia-mediated SOX2 upregulation and prostate cancer cell invasion, the molecular link between SOX2 and HIF-1α in breast cancer cells under hypoxic conditions remains unclear." (PMID 31462898, 2019). "In addition to this, overexpression of HIF-1α has been detected in 69% of the metastatic breast cancers." (PMID 30754624, 2019). "In addition, the analysis of both β-arr1 and HIF-1α transcriptomes in breast cancer shows the overlap of the two gene profiles, including known HIF-1α targets such as those required in neovascularization, and aerobic glycolysis." (PMID 31551935, 2019). "We further show that HIF-1α-positive CBC-tumors were associated with a worse tumor phenotype and a shorter patient survival, corroborating previous data linking HIF-1α to a worse outcome in breast cancer." (PMID 31821370, 2019).
breast cancer (continued). "We found that there was an inverse correlation between the HIF-1α and DNMT3a expression levels in breast cancer cell lines and patient samples, suggesting that DNMT3a may be responsible for methylation of the HIF-1α promoter." (PMID 30940798, 2019). "In breast cancer, the histone methyltransferase Set8 could regulate aerobic glycolysis via stabilizing HIF1α." (PMID 30922330, 2019). "The results show that only H3K9ac expression is upregulated and parallels that of HIF-1α in those breast cancer cell lines with highly malignant behavior, suggesting that H3K9ac may activate HIF-1α gene transcription." (PMID 30940798, 2019). "Consequently, inhibiting pyruvate uptake prevents collagen remodeling even in the context of HIF1α stabilization and thus is effective in impairing metastatic outgrowth of breast cancer-derived lung metastases." (PMID 31069166, 2019). "Although different breast cancer cell lines such as 184A1, SUM149, SUM159, and HCC1954 treated with RA presented a decrease in mammosphere formation, the breast cancer MCF-7 cell line responds to RA with an increase of stemness through an ALDH1A1-retinoic acid-HIF-1α-VEGF pathway." (PMID 31590252, 2019). "On the other hand, HIF-1α knockdown had an opposite effect in mouse lung and mammary tumor cells." (PMID 30634531, 2019). "Western blotting revealed that HIF-1α expression varied among the five breast cancer cell lines." (PMID 30940798, 2019). "We therefore hypothesized that the methylation status of the HIF-1α promoter may be one of reasons to determine its expression levels in different subtypes of breast cancer cell lines and tissue samples." (PMID 30940798, 2019). "Association analysis between HIF-1α, MDR1 and LAPTM4B expression in breast cancer blood specimens." (PMID 30746305, 2019). "Importantly, treatment with the proteasome inhibitor Bortezomib rescued HIF-1α protein expression in P4HA1-silenced breast cancer cells." (PMID 30367042, 2018). "Panel c, the nuclear marker Histone H3 is detectable only in the nuclear fractions of analyzed breast cancer cells, confirming that the experiments were correctly performed and that HIF-1α might indeed be inside the mitochondria." (PMID 29584711, 2018). "For instance, HIF-1α can induce the Rab22-dependent secretion of EVs by human breast cancer cells." (PMID 30206166, 2018). "Whether ADAMTS9 suppresses breast cancer angiogenesis involving HIF1α suppression deserves further studies." (PMID 29193730, 2018). "To verify that unknown effects of CoCl2, separate from HIF1α-stabilizing effects, were not responsible for induction of cancer dormancy, we tested whether CoCl2 could induce dormancy in breast cancer cells in a HIF1α-independent manner." (PMID 30127847, 2018). "Based on these observations, the cross-talk between HIF-1α and Notch signaling pathways may serve as a molecular bridge connecting together the multiple paracrine interactions occurring between breast cancer cells and CAFs toward disease progression." (PMID 29996493, 2018). "However, in estrogen receptor-positive breast cancer cells, estrogen induces activation of HIF-1α and co-operates with hypoxia to regulate the expression of a subgroup of genes." (PMID 29342868, 2018). "In breast cancer, Zhang and colleagues proposed that the exposure of breast cancer cells to hypoxia could stimulate hypoxia-inducible factor (HIF)-1α- and HIF-2α-dependent expression of ALKBH5, which induced m6A demethylation and stabilization of NANOG mRNA." (PMID 29587823, 2018). "Besides, miR-93 expression was found to markedly increase in breast cancer under hypoxia conditions in a HIF-1α-independent manner, mediating the hypoxic regulation with direct TET1 binding." (PMID 29699590, 2018).